POSTN (periostin)
Diseases named in the same sentence as POSTN in open-access papers (continued):
Sharing a sentence is not in itself a finding about the gene and the disease.
tumor (continued). "POSTN, as a small extracellular matrix protein, plays a vital role in the regulation of cell-matrix interaction, which is considered to associate with TME and tumor progression." (PMID 36611136, 2023). "These suggested that high expression of SPOCK1 and POSTN might be correlated with tumor immune evasion in CRC." (PMID 36611136, 2023). "Thus, this suggests that increased periostin levels are correlated with drug resistance, tumor relapse, and tumor angiogenesis." (PMID 37092398, 2023). "On the basis of our results, we speculated that stromal POSTN accelerated metastasis via stromal remodeling capacity and activated the migration of both tumor and stromal cells." (PMID 36765564, 2023). "Still, elevated POSTN mRNA levels in LNs from CC patients is an important contributor in ColoNode assay being one of five biomarkers in the two-triplex assay for prediction of tumor recurrence in CC." (PMID 38156105, 2023). "ECM factors such as periostin, INHBA, MMPs and TGF‐β produced by POSTN+ CAFs could shape the stromal milieu in favour of immune exclusion and tumour growth." (PMID 38115703, 2023). "The expression of periostin (POSTN) by resident pulmonary fibroblasts could alter the extracellular matrix to favor the initial lung colonization of infiltrating tumor cells through activating Wnt signaling in cancer stem cell." (PMID 38037106, 2023). "Taken together, our work shed light on the pro‐tumour and immune‐suppression roles of POSTN+ CAFs, whose targeting may be beneficial to improve ICI response in NSCLC." (PMID 38115703, 2023). "On the basis of our experiments, we speculated that stromal POSTN accelerated metastasis via enhanced stromal remodeling capacity and activated migration of both tumor and stromal cells." (PMID 36765564, 2023). "Our results suggest that POSTN acts at the tumor-proximal intravasation step." (PMID 37069149, 2023). "Tumor periostin levels were also correlated positively with tumor budding." (PMID 35056404, 2022). "Furthermore, POSTN also promotes tumor progression and metastatsis in other cancers such as head and neck squamous cell carcinoma, melanoma, colorectal carcinoma, lung cancer and breast cancer." (PMID 36550569, 2022). "POSTN is involved in the formation of new blood vessels during tumor transformation." (PMID 36077762, 2022). "However, overexpression of POSTN in DDR2-depleted CAFs led to an increase in tumor spreading as measured by sprout area ratio." (PMID 35884543, 2022). "Studies have showed that POSTN is predominantly expressed in tumour stroma." (PMID 36555218, 2022). "Periostin has been identified as a new and powerful angiogenic factor for tumor growth." (PMID 36224629, 2022). "In order to test the effect of DDR2 and POSTN on tumor metastasis, we used DDR2-expressing (CAF shSCRM) and DDR2-depleted CAFs (CAF shDDR2) as well as DDR2-depleted, periostin-overexpressing (CAF shDDR2 POSTN OE), and transfection control (CAF shDDR2 Empty Vector) CAFs." (PMID 35884543, 2022). "Tumor cell xenografts overexpressing POSTN showed higher MVD values compared to control cells, which suggests the involvement of POSTN in blood vessel formation and association with a phenotype of increased tumor angiogenesis and decreased tumor cell apoptosis." (PMID 36077762, 2022). "Tumor periostin was also correlated positively with tumor budding." (PMID 35056404, 2022). "Studies have reported that periostin, in addition to being produced by fibroblasts in a healthy tissue environment, is also produced by CAFs in the tumor microenvironment; therefore, it is involved in tumor development." (PMID 35056404, 2022). "The mesenchymal subtype was characterized by a high FLAIR signal associated with upregulated levels of POSTN, lower ratios of volume of contrast enhancement, and volume of central necrosis, lower levels of non-enhanced tumor, and lower rCBV." (PMID 35330402, 2022). "Knockdown of POSTN inhibited growth and invasion of mesenchymal tumor cells upon chemotherapy." (PMID 35268340, 2022).
tumor (continued). "Further research on the regulations between periostin and cytokines are necessary to understand the interactions between tumor and immune tumor microenvironment, which could be helpful in the development of new targeted therapy." (PMID 35056404, 2022). "The immunofluorescent stains indicated that FR17 intervention successfully down-regulated the expression of LOX, FN and POSTN in the lung induced by tumor-derived factors to impede the construction of PMN, which probably resulted in the decrease in MDSC recruitment." (PMID 35614076, 2022). "The results showed that POSTN may regulate immune molecules in the tumour microenvironment of LUSC via various pathways, thereby exerting a specific role in immune cell infiltration." (PMID 35508298, 2022). "However, works from other teams using POSTN knockout mice showed that POSTN was required for tumor capsule formation." (PMID 36102377, 2022). "Moreover, in this study it also was shown that periostin can promote cancer cell apoptosis, both in vivo and in vitro, and thus contribute to inhibition of the tumor growth." (PMID 35056404, 2022). "Several studies suggested that POSTN could be involved in facilitating the interaction between cancer cells and the tumor microenvironment to promote cell migration." (PMID 35163164, 2022). "It is worthwhile noting that a large panel of cytokines including MCP-1, M-CSF (CSF-1), IL-3, IL-10, IL-12, IL-16, MIP-1β, RANTES, TNF-α and TGF-β2 were upregulated resulting from autocrine effect in POSTN-overexpressing SKOV3 cells leading to potent enrichment of TAMs in the tumor microenvironment." (PMID 36550569, 2022). "Moreover, higher periostin levels were correlated with a number of clinicopathological parameters, such as lymphatic metastasis, vascular invasion and tumor differentiation." (PMID 35056404, 2022). "Many studies have shown that proangiogenic factors and the extracellular matrix protein, i.e., periostin, may be important in tumor angio- and lymphangiogenesis, thus contributing to metastasis formation and worsening of the prognosis." (PMID 36077762, 2022). "Additionally, OmCAFs with high DDR2 and POSTN expression induce tumor cell invasion and in vivo tumor implantation." (PMID 35884543, 2022). "Also, periostin interacts with multiple cell-surface receptors, especially integrins, and triggers signals that promote tumor growth." (PMID 36224629, 2022). "POSTN has been documented to be related to the properties of decrease in intercellular adhesion, induction of angiogenesis, avoidance of immune surveillance, and metastasis potential of tumor cells." (PMID 35832544, 2022). "Anti-POSTN autoantibody can diagnose ESCC patients from normal controls in most subgroups except for patients with family tumor history and moderate and high differentiation, and it showed marginal difference in diagnosing ESCC patients younger than 60 years old (p = 0.0491)." (PMID 35559040, 2022). "We aimed to define the role of DDR2′s modulation of POSTN in CAFs on tumor cell clearance of HPMCs." (PMID 35884543, 2022). "In addition, POSTN functioned as a cell adhesion molecule and participated in many biological processes, including cell adhesion, invasion, metastasis, and tumor angiogenesis." (PMID 35559040, 2022). "In vitro, POSTN promoted lymphatic endothelial cell functions and tumor cell proliferation." (PMID 35567669, 2022). "To determine if DDR2′s regulation of periostin in CAFs has an effect on tumor cell implantation in vivo, we injected ES2 cells and patient-derived CAFs into NCr nude mice and monitored ability to implant and form metastatic nodules in an intraperitoneal xenograft model." (PMID 35884543, 2022). "EMT is a critical step in tumor metastasis, and periostin is involved in both EMT and metastasis." (PMID 36224629, 2022). "POSTN can directly exert its functions on tumor cells in paracrine or autocrine mode." (PMID 35163164, 2022). "The expression level of POSTN also increased in higher tumor sizes (pT)." (PMID 35163164, 2022).
tumor (continued). "Overall, the main source of periostin in tumor tissues is the cancer stroma, especially CAFs." (PMID 36224629, 2022). "In addition, periostin can foster tumor invasion and metastasis by inducing epithelial-to-mesenchymal transition in cancer cells." (PMID 35887333, 2022). "Therefore, the proteins encoded by POSTN and TIMP1 have the possibility of being potential tumor-associated antigens, and we further detected the level of anti-TAA autoantibodies in the subjects’ serum by ELISA experimental." (PMID 35559040, 2022). "Our study revealed a POSTN-integrin-NF-κB-mediated signaling and its involvement in enhancing M2 macrophages and CAFs, which could potentially participate in promoting tumor growth." (PMID 36550569, 2022). "Moreover, lysyl oxidase contributed to periostin-promoted metastatic niche formation and tumor metastasis." (PMID 35719975, 2022). "Finally, proteomic analysis with CPTAC (Clinical Proteomic Tumor Analysis Consortium) mass-spectrometry data further confirmed the up-regulated expression of POSTN protein in BCa tissues, in both paired and unpaired groups." (PMID 35831854, 2022). "Among them, periostin can recruit M2 macrophages, thus augmenting tumor growth." (PMID 36032082, 2022). "Furthermore, it was found that tumor stroma periostin- overexpressed NSCLC patients had a substantially worse survival rate than those with low-expression." (PMID 36224629, 2022). "POSTN is a multifunctional ECM glycoprotein secreted by tumor cells and CAFs." (PMID 36077762, 2022). "Furthermore, statistical analysis demonstrated an increasing level of POSTN (IHC) with an increasing malignancy grade (G) of the tumor in the whole cohort, as well as in AC cases." (PMID 35163164, 2022). "In addition, POSTN expression was more strongly correlated with protumorigenic M2 macrophages than antitumorigenic M1 macrophages in tumor samples." (PMID 34976204, 2022). "In addition, IL6 produced by inflammatory and tumor cells is able to induce POSTN production by CAFs via STAT3 signaling." (PMID 35567669, 2022). "The increased expression of POSTN in CRC was also confirmed (80% of the cases) as compared to healthy intestinal tissues from the tumor margin, which may indicate an important role of the glycoprotein in tumor transformation." (PMID 36077762, 2022). "Compared with normal matrix, POSTN was especially highly up-regulated in cancer-associated stroma cells, indicating that signals derived from tumor cells, TGF-β, for instance, may be the main inducers of POSTN expression in the cancer-associated ECM." (PMID 35831854, 2022). "The functional implication of POSTN on these important biological processes taking place during the metastatic cascade was illustrated in two murine models (ear sponge assay and intra-nodal injection of tumor cells) using neutralizing anti-POSTN antibodies and the recombinant protein." (PMID 35567669, 2022). "These factors may explain the contradictory function of periostin as a tumor suppressor or progressor." (PMID 36224629, 2022). "We aimed to study the effect of DDR2′s modulation of POSTN in CAFs on tumor cell attachment." (PMID 35884543, 2022). "We used the tumor spheroid assays to determine whether POSTN expression in CAFs influences tumor spheroid branching." (PMID 35884543, 2022). "In fact, periostin induces tumor growth via promoting cell proliferation or escaping apoptosis." (PMID 36224629, 2022). "The correlation between these molecules may indicate the participation of TNFα in the regulation of periostin levels in the tumor microenvironment." (PMID 35056404, 2022). "And POSTN is found to play an important role in promoting tumor cells acquiring those properties." (PMID 35832544, 2022). "We identified that POSTN had significantly higher expression in the DDR2-expressing NOFs co-cultured with ES2 tumor cells compared to conditioned media of NOF alone or DDR2-depleted NOFs co-cultured with ES2 tumor cells." (PMID 35884543, 2022).
tumor (continued). "Targeting periostin- and IL-6- mediated tumor-stroma interaction may be an attractive therapeutic strategy for human colorectal tumors." (PMID 36077762, 2022). "Furthermore, we successively evaluated the contribution of POSTN to bone metastasis of PCa cells by intracardiac injection of tumor cells in mice." (PMID 35087756, 2021). "Comparing its expression between individual tumors, POSTN is consistently expressed in tumor fibroblasts, but is expressed in cancer cells in only two of the five tumors, suggesting that stromal Postn expression is regulated differently than in epithelial cells." (PMID 34809697, 2021). "Periostin, as a stromal factor for healthy stem cell micro-environment, plays a crucial role during metastatic colonization for the maintenance and expansion regulation of CSCs to promote tumor metastasis." (PMID 34858996, 2021). "Moreover, periostin+CAF abundance in the TME appears essential for tumor cell dissemination, potentially contributing to the biological differences between CSCCLNM and CSCCnon‐LNM tissues." (PMID 33124726, 2021). "CAFs and tumor cells need reciprocal communication to stimulate mediators such as vimentin, matrix metalloproteinase (MMPs); periostin; Insulin growth factor-2 (IGF2); IL-33; and CXCL12, related to and tumor growth, invasion, and downregulation of tumor suppressor genes." (PMID 34204259, 2021). "The authors found that in plaque-stage MF, periostin-stimulated macrophages are the dominant factor in the formation of the tumor mass and, after the plaque stage, M2-like macrophages are dominant in maintaining an immunosuppressive tumor microenvironment." (PMID 34685762, 2021). "Also, upregulation of POSTN gene expression and establishment of its role in tumour lymphangiogenesis, making it evident that this can be used as a potential biomarker for OSCC46,47." (PMID 33739025, 2021). "In this study, we found that the upregulated protein expression of POSTN in the tumour microenvironment promoted the direct binding of the transcription factor AP-2α to the CD133 promoter region and therefore enhanced the expression of the CD133 gene in HCC cells." (PMID 34193219, 2021). "In addition, POSTN was decreased in the tumor tissue transduced with POSTN-knockdown cells through IHC analysis." (PMID 34093819, 2021). "Periostin also recruits circulating immunoinhibitory M2 macrophages into the tumor parenchyma." (PMID 33178210, 2020). "Periostin, a secretory protein that can alter the remodeling of the ECM, was found to be highly expressed in gastric tumors and to be positively associated with gastric cancer metastasis by promoting tumor metastasis and invasion." (PMID 32046329, 2020). "In CTCL, fibroblast-derived periostin mediated TSLP production by keratinocytes that in turn directly stimulated in vitro tumor cell growth in TSLPR-expressing tumor cells, and in vivo TSLP inhibition reduced tumor formation in EL-4 and MBL-2 cell mouse models." (PMID 33042121, 2020). "Moreover, the IHC analysis of POSTN showed significant relationships between the glycoprotein and the clinicopathological data of patients (e.g., clinical cancer stage, tumour size, or lymph node involvement)." (PMID 32987711, 2020). "Contrary to miR-876, POSTN was increased in HCC tumor cells and clinical tissues." (PMID 33083453, 2020). "In addition, the Mann–Whitney U test demonstrated an increasing level of POSTN expression in CAFs as the malignancy grade (G) of the tumour increased." (PMID 32987711, 2020). "Additionally, a significantly higher expression level of POSTN in CAFs was noted in pT3-pT4 as compared to pT1 tumours in the whole cohort of patients and in the AC cases (*** p < 0.001, ** p < 0.005, * p < 0.05, respectively; Mann–Whitney U test)." (PMID 32987711, 2020). "Moreover, periostin is predominantly found in collagen-rich fibrous connective tissues in multiple organs and promotes tumor growth and metastasis." (PMID 33126642, 2020).